CD4 (CD4 molecule)
Diseases named in the same sentence as CD4 in open-access papers (continued):
Sharing a sentence is not in itself a finding about the gene and the disease.
tumor (continued). "We also showed that HS-1793 exhibits its anti-tumor effect through enhancing anti-tumor immunity by reducing the CD4 + CD25+ regulatory T cells at 1.25 to 5 μM." (PMID 24403520, 2014). "It is well established that the aggregation of CD4+CD25+ Treg cells in the tumor milieu is involved in the immune escape of tumors and is detrimental for immunotherapy among tumor patients." (PMID 24741609, 2014). "PD-L1 is the primary PD-1 ligand that is up-regulated in solid tumors, whereit can inhibit cytokine production and the cytolytic activity of PD-1+tumor-infiltrating CD4+ and CD8+ T cells." (PMID 24502656, 2014). "We now have a better understanding of the CD4+ suppressor/Tregs and their influence on the generation of a productive anti-tumor immune response." (PMID 24273748, 2013). "T lymphocytes, particularly CD4+ and CD8+ T lymphocytes, play a leading role in the anti-tumor function in vivo; therefore, the quantities of CD4+ and CD8+ T lymphocytes are crucial for killing the cancer cell." (PMID 24137307, 2013). "CD4+ T cell infiltration in the tumor was enhanced by the combination treatment, and a gemcitabine-associated decrease in proliferating tumor-infiltrating CD8+ T cells was partly rescued by CTLA-4 blockade." (PMID 23626745, 2013). "The percentage of peripheralblood and intra-tumor CD4+ and CD8+ cells were assessed by flow cytometry." (PMID 23700562, 2013). "We further focused on the interaction of CD4+ T cells with tumor cells by visualization of the contact formation." (PMID 24205259, 2013). "Western blot results indicated abundant GzmB expression in cytotoxic cells, even in CD4+T cells which also underwent apoptotic cell-in-cell death inside tumor cells." (PMID 24113190, 2013). "Alternatively, it appears that such CD4 T cell subsets and their signature cytokines can also contribute and facilitate tumor-promoting activities." (PMID 23533029, 2013). "The proportion of Treg cells in sham normal mice spleen was 16.15% of all CD4+ T cells, while sham tumor-bearing mice exhibited a 1.74-fold increase of Treg cells (28.1% of the CD4+ population)." (PMID 24314291, 2013). "Immune effector cells that have been recognized for their contribution to an anti-tumor response are numerous and, in addition to CD4 and CD8 T cells, include natural killer (NK), natural killer T cells (NKT), macrophages, and neutrophils." (PMID 24265631, 2013). "In parallel, tumour infiltration by CD4, CD8 and Foxp3 regulatory T cells was evaluated by immunohistochemistry and correlated with TCR-sequencing data." (PMID 24122851, 2013). "The chief input of CD4+ T cells for anti-tumor effects operates through the direct help for the generation/augmentation of tumor-specific CTL responses and/or indirect help through secretion of various cytokines, such as IL-2 and IFN-γ." (PMID 24066030, 2013). "Addition of both chemokines in this study showed additional benefits in survival and tumor rejection, with significant CD4+ and CD8+ T cell infiltration in TME." (PMID 24967094, 2013). "Although there are only few reports that CD3+CD8− T cells possess cytotoxic potential, recent studies have demonstrated that CD4+ T cells can also exhibit a strong cytotoxic activity that results in inhibition of tumor development." (PMID 23922758, 2013). "Once CD4 T cells are reactivated at the tumour site, their expression of IFN-γ and TNF-α that we measured has multiple potential anti-tumoural consequences." (PMID 23717511, 2013). "IL-1β promoted IL-17 production from CD4+ T cells, which in turn attenuated the anti-tumor effect of chemotherapy via an IL-17-dependent proangiogenic effect." (PMID 24409181, 2013). "While CD8+ T-cell ablation alone resulted in uncontrolled tumor growth, additional Treg depletion enabled the CD4+ T cells to reject the tumor." (PMID 22890822, 2013).
tumor (continued). "Combination immunotherapy in ProHA × TRAMP mice resulted in a significant increase in anti-tumor TH1 CD4 cells within the local tumor environment and in the draining lymph nodes." (PMID 23557194, 2013). "The murine studies reported here also show that the recombinant yeast-brachyury can elicit both CD8+ and CD4+ T-cell responses in vivo as well as anti-tumor activity." (PMID 24125763, 2013). "Although the role of CD4 T cells in the antitumor response remains under investigated, it is becoming clear that effective immune responses to a developing or progressing tumor requires their activation, maturation, and active participation." (PMID 23533029, 2013). "In this study we investigated polarisation of tumour-reactive CD4 T cells and its impact on homing to the brain of mice bearing an intracranial tumour." (PMID 23717511, 2013). "In this retrospective case-control study, we examined the prognostic value of FOXP3 with respect to recurrence of OSCC taking into account the subcellular localization of FOXP3 within CD4+tumor infiltrating cells." (PMID 23977174, 2013). "Our finding that Tregs preferentially influence the anti-tumor CD4+ T-cell immune response revealed several aspects that had not been reported previously." (PMID 22890822, 2013). "We show here that there is an expansion of tumor-specific CD4+ T cells producing cytokines and cytotoxic molecule granzyme B (GzmB) in the early phase of tumor growth." (PMID 22890822, 2013). "Upon activation, CD8 cytotoxic T cells (CTLs) directly eliminate tumor cells while CD4 T helper cells (Th) stimulate B cells supporting both humoral and cytotoxic responses." (PMID 23577028, 2013). "Inhibition ofRANKL production by tumor-primed CD4+ T cells protects mice fromosteolytic disease and, surprisingly, completely abolishes the development of bonemetastases." (PMID 23935856, 2013). "The analysis performed 10 days after tumor injection showed that the vast majority (around 80%) of tumor-infiltrating CD4+CD25+ cells derived from expansion/recruitment of the transferred Treg, rather than from conversion of non-Treg." (PMID 23986759, 2013). "In our studies, the vaccine-induced immune response after treatment with PC61 and fusion cells consisted primarily of tumor-specific CD4+ T cells." (PMID 23768240, 2013). "Conversely, using DC-STAMP promoter driven construct linked to OVA, resulted in strong OVA-specific CD4+ and CD8+ T-cell responses in vitro and in vivo and protected mice against OVA+ tumor challenge." (PMID 24228179, 2013). "We also performed in vivo tumor challenge studies in the presence of GR20 antibody that blocks IFN-γ Rα, showing that WT MMC tumor cells were rejected by CD4-depleted and GR20-treated FVB mice." (PMID 24324806, 2013). "Based on this data, one possibility is that the presence of human CD4+Nrp1+CD25high T in lymph nodes cooperates with the tolerogenic microenvironment of tumor burden areas." (PMID 24324469, 2013). "In both murine models and cancer patients, tumors are enriched in arginase I-producing MDSC, and arginine metabolism in the tumor microenvironment leads to downregulation of CD3ζ chain and suppression of proliferative capacity in both CD4+ and CD8+ T cells." (PMID 23874338, 2013). "Clinical studies have shown that CD4+CD25+ cells are often present within the tumor mass, and have reported a link between a presence of a tumor and an increase in the proportion and/or the number of CD4+CD25+ Tregs in the blood." (PMID 24133490, 2013). "Although CD4+T cells have been shown to have direct killing activity against tumor in selected settings, it is a common consensus that these cells show their full potential by coordinating effector arms of the immune responses, i.e., helper function." (PMID 24066030, 2013). "Outcomes of interest include tumor response to therapy, effect on CD4 count and viral load, and changes in function of HIV-specific T cell function." (PMID 24383025, 2013).
tumor (continued). "We interpret this observation to mean that the requirement for CD4+ T cell help for vaccines therapeutic efficacy, irrespective of its mechanistic nature, has already been fulfilled by priming with the tumor." (PMID 24066030, 2013). "In a mouse lung carcinoma model, IL-3 enhanced tumor rejection by enhancing cytotoxic effectors through a mechanism that required CD4+ cells." (PMID 23441198, 2013). "We demonstrated that in vivo depletion of Tregs and CD8+ T cells in FBL-3-bearing DEREG transgenic mice augments GzmB production by CD4+ T cells and increases FV-specific CD4+ T-cell effector and cytotoxic responses leading to the complete tumor regression." (PMID 22890822, 2013). "The data demonstrate that mainly CD8+ T cell-mediated rejection of FBL-3 tumor cells but CD4+ T cells had only a minor effect." (PMID 22890822, 2013). "The effect of type 1 IFNs on the generation of antigen-specific CD4+ T cells in vivo is expected to help the induction of an anti-tumor response during the vaccination steps of the NDV-DC therapy." (PMID 24833054, 2013). "In the current study, we report that Tim-3+ CD4 T cells accumulate in human tumor tissues, and that Tim-3 expression defines a subset of regulatory T cells (Tregs) in several types of human tumors." (PMID 23526963, 2013). "Immunostaining of tumors revealed significantly less tumor associated immune response in CalpTG animals as assessed by analyzing the number of CD3+, CD4+, CD8+ and NK cells (n = 10/group)." (PMID 23565252, 2013). "Purified CD4+ splenic T cells were tested for reactivity in vitro to CEA protein 29 days post-tumor transplant." (PMID 23894654, 2013). "Natural killer (NK) cells, which are another important effector cell type that has direct killing activity against tumor, have recently been shown to require CD4+ T cell help via IL-2." (PMID 24066030, 2013). "One report showed that tumor-infiltrating IFN-γ+ CD4+ T cells were increased in IL-17−/− mice compared with WT mice; conversely, another report showed that these cells were decreased in IL-17−/− mice." (PMID 23372655, 2013). "Compared to untreated tumor-bearing mice, PTT-treated mice had significantly increased levels of infiltrating CD8+ and CD4+ T cells in the contralateral tumor." (PMID 23935927, 2013). "By exposing the CellVue-labeled tumor cells to lymphocytes we were able to detect a positive fraction with CellVue induced fluorescence on CD4+ T cells indicating a transfer of parts of cell membrane of the tumor cells to the surface of lymphocytes." (PMID 24205259, 2013). "It is likely that the tumor-infiltrating CD4+ T cell pool is highly heterogeneous comprising both Foxp3+ and Foxp3− suppressor cells." (PMID 23874342, 2013). "A 2.6-fold increase in CD4 T cells extracted from tumor-draining lymph nodes was observed in mice treated with 4-1BB Ab compared to untreated mice." (PMID 24829750, 2013). "Strikingly, protective effects induced by the different protocols of cancer vaccination were related and dependent on increasing number of tumor infiltrating CD4+granzyme+ T cells and decreasing concentration of Treg." (PMID 23663506, 2013). "To analyze the total populations of CD4+ and CD8+ T cells that were activated during tumor rejection, we used the maker CD154 (CD40L) for CD4+ T cells and the activation-associated glycoform of CD43 for CD8+ T cells." (PMID 22890822, 2013). "The effect of TGF-ß on the conversion in vivo in tumor-bearing mice was addressed more recently using adoptive transfer of CD4+25−Foxp3−T-cells into Rag−/− mice." (PMID 24133490, 2013). "CD4+ T cells play an important role in activation of CD8+ effector cells for immune responses against tumours and viruses, and also in autoimmune inflammation." (PMID 25400914, 2013). "We previously demonstrated the key role played by the CD8+ and CD4+ T-cell compartments in tumor immune eradication of WEHI-164 tumor-bearing mice subjected to L-M therapy." (PMID 24156020, 2013).
tumor (continued). "Remarkably, tumor-induced activation of Foxp3− CD4+ T cells in drLN also resulted in their differentiation into GzmB-producing cells, suggesting a potential cytotoxic role for these cells." (PMID 22890822, 2013). "Several studies reported that cytotoxic CD8+ T cells and T helper CD4+ T cells infiltrated in the tumor tissue lead to a reduction of the tumor growth." (PMID 24312450, 2013). "The major anti-tumor effectors are memory (CD45RO+) cytotoxic CD8+ T cells while more complex is the role of CD4+ T cells that depends on the pattern of cytokines produced." (PMID 23950747, 2013). "Using this model, it was determined that, as in human CRLM, there were low levels of TIL overall and decreased levels of CD3 and CD4+ T-cells compared to non-tumor liver parenchyma." (PMID 23514280, 2013). "Collectively, the data demonstrate a local expansion of tumor-specific T cells with the CD4+ T-cell response developing more rapidly than the CD8+ T-cell response." (PMID 22890822, 2013). "Increased tumor-derived NeuGcGM3 ganglioside in sentinel lymph nodes have been suggested to directly influence coordinated interactions between DC and both helper and regulatory CD4+ T cells abrogating an anti-tumor-specific immune response." (PMID 24381785, 2013). "CD4 T cells are necessary elements for priming tumor-specific CD8 T cells, influencing the differentiation and expansion of tumor antigen-specific CTLs and are essential for generating and maintaining long-term CD8 memory T cell responses." (PMID 23533029, 2013). "Redirected CD4 T cells provide an opportunity for direct destruction of the tumor by the effector CD4 T cells." (PMID 23970885, 2013). "Effective cancer vaccines are designed to boost host adaptive immunity from a functionally tolerized state against cancer cells to one that can mount a functionally competent, tumor-specific, CD4+ and CD8+ effector and memory T cell-mediated immune response." (PMID 24967094, 2013). "When tumour cross-sections were analysed by immunohistochemistry, S12.5 tumours were found to have a significant increase in CD4+ and CD8+ cells compared with SCCVII tumours." (PMID 24251770, 2013). "Second, after mAb PC61-treatment, we observed increased frequencies of vaccine-induced CD4+ T cells that secreted IFN-γ upon stimulation with tumor cells." (PMID 23768240, 2013). "CD4+ T cells prime tumor-specific Tc cells so that these CD8+ T cells can directly lyse tumor cells." (PMID 23667456, 2013). "Among these lymphocytes, CD4+ T cells primarily mediate graft anti-tumor effects, whereas CD8+ T cells play an important role in the occurrence of GVHD." (PMID 24040055, 2013). "CTLA-4 blockade and GVAX treatment resulted in an increase in the ratio of tumor antigen-specific CD4 and CD8 Teffs to Tregs." (PMID 23557194, 2013). "The present study showed that the expression of Tim-3 is upregulated on tumor-infiltrating CD4 T cells." (PMID 23526963, 2013). "In a more recent study, all four T cell clones isolated from CML patients after BMT, which had exhibited cytotoxicity for autologous tumor cells, were immunophenotyped as CD4+CD8− cells." (PMID 24348684, 2013). "The equally beneficial roles of Th1 and Th2 CD4 cells in our long term tumour therapy experiments were unexpected in view of the very clear advantages for Th1 transfer in short term experiments." (PMID 23717511, 2013). "Our study illustrated major functional consequences of CD4 T cell infiltration into intracranial tumours that augmented CD8 T cell recruitment, the local cytokine milieu, and ultimately anti-tumour immunity." (PMID 23717511, 2013). "Since in our experiments tumors were successfully eradicated, and development of anti-tumor resistance was observed, we can presume that both CD4+ and CD8+ cells were present." (PMID 23360213, 2013). "The acquisition of cytotoxic activity by tumor-reactive CD4+ T cells is particularly striking since it only emerged when the suppressive function of Tregs was blocked." (PMID 22890822, 2013).
tumor (continued). "Our data suggest that IL-27 signals are indispensable for IFN-γ production by CD4+ T cells in tumor immunity." (PMID 23554861, 2013). "While in the FVB (an inbred strain of mice) genetic background CD8+ T cells are thought to be more important in tumor promotion, in the C3H background, CD4+ T cells are thought to be tumor-promoting while CD8+ T cells are considered to be protective." (PMID 24403255, 2013). "In the tumor microenvironment, accumulating CD4+CD39+ iTreg expand upon induction by TA, DC products, and selected cytokines and up-regulate CD73, acquiring the capability to utilize ADO for mediating suppression of other immune cells." (PMID 23898333, 2013). "This study shows that tumor-specific CD4+ T cells are able to protect against virus-induced tumor cells." (PMID 22890822, 2013). "SA-4-1BBL was also reported to inhibit the formation of induced Treg (iTreg), that normally limit T-cell immune response in the tumor micro-environment, and to make CD4+ and CD8+ effector T-cells (TEff) cells refractory to Treg activity." (PMID 23840967, 2013). "Ovarian sections from another set of hens (n = 26) were assessed to verify tumor type and stage and to count CD4, CD8 and Bu1a immunostained cells by morphometric analysis." (PMID 24040191, 2013). "Combination therapy resulted in skewed local and systemic expansion of the HA-specific CD4 T cell compartment toward an anti-tumor, IFN- γ+ phenotype." (PMID 23557194, 2013). "Our experiments showed the combination therapy significantly decreased the frequency of Tregs, and increased CD8+ T cells and CD4+ T cells at tumor sites." (PMID 24304581, 2013). "This is not without precedence and in accordance with several studies, which have demonstrated that CD4+ T cells play a pivotal effector role during tumor rejection." (PMID 23768240, 2013). "Identification of further tumour antigens recognised by CD4 T cells will therefore maximise opportunities of designing efficacious cancer immunotherapies." (PMID 23717511, 2013). "Here, we compared the kinetics of the CD4+ T-cell response to FBL-3 tumor antigen in drLN with the CD8+ T-cell response and found a more rapid development of the CD4+ T-cell response after FBL-3 injection." (PMID 22890822, 2013). "With respect to anti-tumor responses, it appears that upon cell transfer Th1 and Th17 are the most potent CD4 T cell subsets." (PMID 24265631, 2013). "We propose that Tim-3+ CD4 T cells exhibit different phenotypes and functions during the process of tumor progression." (PMID 23526963, 2013). "In contrast, HSP70 expressed on the tumor cell surface has been shown to promote innate and adaptive immune responses, including enhanced T-cell activation and promotion of CD4+ and CD8+ cytotoxic immune responses." (PMID 23894654, 2013). "In DT-treated DEREG mice challenged with tumor cells for 6 days, we observed a significant increase in the mean percentage of tumor-specific (tetramer II+) CD4+ T cells in comparison with mice that received only FBL-3 cells." (PMID 22890822, 2013). "IFN-γ production by CD4+ Th1 cells can up regulate MHC molecules on tumor cells, leading to enhanced CTL and Th responses." (PMID 24066030, 2013). "The CFSE-based Treg suppression assay was performed by co-culturing CD4+CD25+ Tregs and CD4+CD25− responder T cells (Tresps) (CFSE stained) isolated from the spleens of PC tumor-bearing mice." (PMID 23874581, 2013). "Our results are compatible with a recent study that showed decreased percentages of splenic CD4+CD25+ Tregs in tumor-bearing BALB/c mice after 8 weeks of physical activity." (PMID 24312199, 2013). "In contrast to this dogma recent reports revealed participation of CD4+ T cells as powerful effector cells with capacity for direct action against tumor cells leading to regression of the tumor." (PMID 24205259, 2013).